SNORD90 (small nucleolar RNA, C/D box 90)
Synonyms: HBII-295
Gene: Small nucleolar RNA gene on chromosome 9 (122,880,213 to 122,880,323, reverse strand). Ensembl gene ENSG00000212447.
Gene Ontology:
Biological process: RNA processing
Cellular component: nucleolus
Homologues: Orthologues: macaque SNORD90 (97% identical), chimpanzee SNORD90 (95% identical), rabbit SNORD90 (89% identical), guinea pig SNORD90 (88% identical), dog SNORD90 (87% identical), pig SNORD90 (87% identical), rat Snord90 (87% identical), mouse Snord90 (86% identical).
Diseases named in the same sentence as SNORD90 in open-access papers:
SNORD90 is named in the same sentence as 1 disease in open-access papers, as found by Europe PMC text mining. Sharing a sentence is not in itself a finding about the gene and the disease. The quoted sentences say what the papers report.
Anxiety (1 paper, 2023). Intense feelings of nervousness, tension, or panic often arise in response to interpersonal stresses. "We over-expressed Snord90 or a full scrambled Snord90 sequence control in male mouse cg1/2 via bilateral injections of an adeno-associated virus (AAV) followed by a battery of behavioural tests designed to measure anxiety and depressive-like behaviors in mice." (PMID 37432876, 2023). "Overall, our results consistently showed that over-expressing Snord90 levels in cg1/2 yielded decreased emotionality indicative of a decrease in anxiety-like and depressive-like behaviours." (PMID 37432876, 2023).